INS (insulin)
Diseases named in the same sentence as INS in open-access papers (continued):
Sharing a sentence is not in itself a finding about the gene and the disease.
type 2 diabetes (continued). "Regular aerobic exercise has been extensively proven to contribute to fat loss, and an improvement in insulin sensitivity, and reduce cardiovascular risk in type 2 diabetes patients." (PMID 39458447, 2024). "The results showed that CK can reduce blood sugar levels and increase insulin sensitivity in type 2 diabetes caused by a high-fat diet and fasting." (PMID 38534764, 2024). "The metabolomic signature of type 2 diabetes included most fasting insulin-associated signals (38 out of 42), except for degree of unsaturation in fatty acids, acetone, phospholipids in medium HDL, and total lipids in medium HDL." (PMID 38459184, 2024). "Older adults are more glucose intolerant and insulin resistant than the younger ones having a higher risk of developing type 2 diabetes mellitus (T2DM)." (PMID 37857994, 2024). "That distinguishes them from type 1 diabetes caused by autoimmune destruction of the β cells and type 2 diabetes with defective insulin secretion by the β cells and the inability of insulin-sensitive tissues to respond appropriately to insulin." (PMID 38855865, 2024). "Type 2 diabetes (T2D) is a chronic metabolic disease, characterized by progressive loss of insulin secretion and hyperglycemia, ultimately resulting in adverse clinical complications." (PMID 38535319, 2024). "Increased levels of circulating BCAAs have been described in insulin-resistant individuals and linked to a higher risk of type 2 diabetes." (PMID 38910152, 2024). "Fasting has been related to better cardiovascular health (blood pressure, cholesterol and triglycerides profiles), as well as with enhancing insulin sensitivity, promotion of weight loss, and prevention and treatment of type 2 diabetes (T2D)." (PMID 39560850, 2024). "Dysregulation of insulin action has been associated with the pathophysiology of schizophrenia and type 2 diabetes." (PMID 39734678, 2024). "Dairy proteins, especially whey proteins, are associated with improved insulin sensitivity and a reduced risk of type 2 diabetes." (PMID 38257161, 2024). "In this this real-world study using a global federated dataset, we aimed to evaluate the impact of SGLT2i and GLP1-ra therapy on the risk of diabetic retinopathy and DMO in individuals with type 2 diabetes taking insulin." (PMID 38584180, 2024). "The treatment of type 2 diabetes is approached comprehensively, incorporating strategies that aim to control blood glucose, improve insulin sensitivity and manage related risk factors." (PMID 38794296, 2024). "Postprandial insulin secretion has been associated with metabolic disorders such as hyperlipidemia and type 2 diabetes." (PMID 38263222, 2024). "This interaction is caused by mutations, resulting in an altered insulin structure and causing its altered action, hyperinsulinemia, and the development of adult-onset diabetes with autosomal dominant inheritance." (PMID 38542928, 2024). "Mitochondria, as crucial regulators of insulin secretion, are closely linked to the onset of type 2 diabetes." (PMID 39763653, 2024). "Within the pancreatic islet, multiple cell types have been implicated in type 2 diabetes progression, most notably beta cells which secrete insulin in response to glucose stimulation, but also other cell types including alpha cells and delta cells." (PMID 38967666, 2024). "Type 2 diabetes (T2D) is a multifaceted disease with a rising prevalence and is characterized by beta cell failure and varying levels of insulin resistance, causing blood glucose levels to rise toward hyperglycemia." (PMID 39108361, 2024). "Metformin, a key anti-diabetic drug, not only reduces liver glucose production and improves insulin sensitivity but also promotes A. muciniphila proliferation, helping to lower the risk of type 2 diabetes (T2D)." (PMID 39339675, 2024). "About 25% of people in the general population are insulin resistant, increasing the risk for type 2 diabetes (T2D) and metabolic disease." (PMID 38032738, 2024).
type 2 diabetes (continued). "In recent decades, research has demonstrated the impact of vitamin D deficiency on glucose metabolism, insulin secretion, and the development of type 2 diabetes." (PMID 38216955, 2024). "We have validated ALDH1a3 as an essential driver of pancreatic β cell loss whose inhibition restores insulin secretion in late-stage type 2 diabetes." (PMID 39133222, 2024). "CACNA1E was selected as a candidate gene because of their previously reported role in the risk of type 2 diabetes, insulin resistance, impaired insulin secretion and regulation of β-cell function." (PMID 38932873, 2024). "The correlation between Type 2 diabetes and an increased vulnerability to cancer is believed to be linked to elevated levels of blood sugar, insulin, and body weight." (PMID 39758344, 2024). "Higher mg levels are linked to improved insulin sensitivity, which helps regulate blood sugar levels and reduces the risk of type 2 diabetes." (PMID 39539878, 2024). "An imbalance in the gut microbiota can reportedly lead to abnormal insulin signaling and chronic low-grade inflammation, which are major causes of type 2 diabetes." (PMID 38674796, 2024). "Regular physical activity aids weight control, reduces abdominal adiposity, and enhances insulin sensitivity, reducing type 2 diabetes risk." (PMID 38469145, 2024). "This dual action on both inflammation and insulin signaling positions BHB as a promising candidate for metabolic interventions aimed at reducing the risk of type 2 diabetes and improving metabolic flexibility." (PMID 39728460, 2024). "Recent studies have demonstrated that secreted frizzled-related protein 4 (SFRP4) is a potential biomarker for β-cell dysfunction in type II diabetes, associated with reduced insulin secretion." (PMID 39840111, 2024). "HF itself is considered an insulin-resistant state and is associated with a significant risk for the future development of type 2 diabetes." (PMID 39583100, 2024). "We found some evidence linking chocolate consumption with lower blood pressure, lower risk of type 2 diabetes, and improved insulin markers, but the evidence was ranked low or very low." (PMID 39781269, 2024). "Congruent results were noted to ascertain the antidiabetic effect on Streptozotocin (STZ)-induced type 2 diabetic mice based on weight loss prevention and improvements in fasting blood glucose and insulin levels." (PMID 39000608, 2024). "First, the management of pregnant women with pre-existing type 1 and type 2 diabetes is more complex than women with gestational diabetes due to their higher risk of experiencing serious perinatal complications and the need for insulin therapy." (PMID 38163872, 2024). "Elevated levels of SELENOP are associated with decreased insulin sensitivity and an increased risk of type 2 diabetes." (PMID 39149550, 2024). "The restoration of first-phase insulin response is a well-established observation caused by weight loss in type 2 diabetes." (PMID 38890501, 2024). "This study aims to examine the association between insulin use and cardiovascular effects in type-2 diabetic patients with uncontrolled hyperglycemia." (PMID 39295783, 2024). "Similar to the sphingolipids, phosphatidylcholine plays an integral role in regulating metabolism, and disbalances have been implicated in the pathophysiology of type 2 diabetes and insulin signalling." (PMID 38396205, 2024). "One of the main features of many metabolic diseases-type 2 diabetes- is linked to cognitive impairment is reduced insulin sensitivity." (PMID 38840158, 2024). "As individuals age, their risk of developing type 2 diabetes increases due to factors such as poor diet, sedentary behavior, weight gain, reduced insulin sensitivity, and changes in body composition, including increased body fat and decreased muscle mass." (PMID 39867544, 2024). "B cells are known to be involved in type 2 diabetes because B cell-deficient DIO mice have an increased insulin sensitivity." (PMID 39606781, 2024).
type 2 diabetes (continued). "Positive associations between NAFLD and circulating insulin levels, insulin resistance (IR), type 2 diabetes (T2D), and obesity have been found." (PMID 39045929, 2024). "Coffee consumption has been linked to improved insulin sensitivity and a reduced risk of type 2 diabetes, which can indirectly benefit liver health by reducing the metabolic burden on the liver." (PMID 38999772, 2024). "Lower 25(OH)D levels have also been linked to impaired glucose-stimulated insulin secretion and β-cell function, contributing to hyperglycemia in individuals with type 2 diabetes." (PMID 38551916, 2024). "Increased circulating levels of 3-indolepropionic acid, a tryptophan catabolite, have been associated with improved insulin secretion and sensitivity and a decreased risk of type 2 diabetes." (PMID 38910152, 2024). "This genetic susceptibility to type 2 diabetes is associated with genes that control insulin secretion and function, as well as those that impact factors like obesity." (PMID 39605770, 2024). "Dietary patterns profoundly affect insulin sensitivity, metabolic syndrome, obesity, cardiovascular disease, and type 2 diabetes risk (T2D)." (PMID 39275236, 2024). "Insulin resistance (IR), referred as decreased insulin sensitivity, is a fundamental abnormality of type 2 diabetes and an important risk factor of hypertension." (PMID 38278849, 2024). "Type 2 diabetes is characterized by hyperglycemia and hyperphagia, and both insulin and leptin deficiency can explain this." (PMID 38707092, 2024). "It is important to treat diabetes type 2, which is characterized by progressive loss of beta cells and decreased output of insulin as a result of resistance to insulin." (PMID 38926327, 2024). "Previous studies have demonstrated that miR-375 regulates insulin exocytosis and is associated with type 2 diabetes." (PMID 38397233, 2024). "Multivariable MR analysis also found that genetically proxied BMI, fasting insulin levels, and type 2 diabetes partially mediated the associations of LST and MVPA with several gastrointestinal diseases." (PMID 38583262, 2024). "For type 2 diabetes, lifestyle modifications such as weight loss and exercise are key to enhancing insulin sensitivity and preserving β-cell function." (PMID 39560873, 2024). "Notwithstanding, an increase in protein intake has been shown to improve insulin sensitivity by maintaining muscle mass during weight loss in elderly patients with prediabetes or type 2 diabetes." (PMID 38257161, 2024). "This decrease in expression potentially impairs insulin signaling pathways, escalating the risk of developing metabolic disorders, notably type 2 diabetes and metabolic syndrome." (PMID 38337650, 2024). "A similarity between the pathologies associated with Alzheimer’s disease and type 2 diabetes was first postulated by Hoyer in 2002, because both diseases exhibit declines in glucose uptake, insulin levels, insulin binding, and tyrosine kinase activity." (PMID 39683565, 2024). "Type II diabetes is mainly caused by defects in insulin secretion and absorption, resulting in the inability of insulin function." (PMID 39420727, 2024). "The advantages of a diet that supports optimal insulin levels include improved blood sugar control, enhanced metabolism, reduced risk of type 2 diabetes, better weight management, and overall support of long-term health." (PMID 39606544, 2024). "This was accompanied by smaller pancreatic islets and reduced insulin gene expression, leading to impaired glucose metabolism and an increased risk of type 2 diabetes and other metabolic diseases later in life." (PMID 39770898, 2024). "Previous studies have revealed that a higher level of indolepropionate was associated with a lower risk of type 2 diabetes and increased insulin secretion." (PMID 38326796, 2024).
type 2 diabetes (continued). "Type 2 diabetes begins with a gradual decline in insulin effectiveness, causing the body to struggle with glucose transport into tissues and leading to insulin receptor desensitization." (PMID 39588429, 2024). "While insulin treatment can cause adverse side effects like hypoglycemia and weight gain in any population, older adults with type 2 diabetes are particularly vulnerable to hypoglycemia." (PMID 39457586, 2024). "C-peptide has been substituted for insulin in the homeostasis model assessment (HOMA2) B calculation to identify individuals with severe insulin-deficient type 2 diabetes (SIDD)." (PMID 38654804, 2024). "This study aimed to assess the effects of purified cafestol on insulin sensitivity and other metabolic parameters in healthy individuals with increased waist circumference at risk of developing type 2 diabetes." (PMID 39408200, 2024). "Type 1 is caused by the autoimmune destruction of pancreatic beta cells, while type 2 diabetes is associated with insulin resistance or reduced insulin secretion." (PMID 39323638, 2024). "Other prebiotics such as RS have been shown to increase insulin sensitivity and reduce the risk of type 2 diabetes." (PMID 39481540, 2024). "Another isoflavone, genistein, is metabolised by gut bacteria and has been found to improve insulin signalling and reduce fat accumulation in the liver, a known risk factor for obesity and type 2 diabetes." (PMID 38450400, 2024). "Resistant starches are positively linked to type 2 diabetes prevention by improving insulin sensitivity, lipid profile, and gut microbiota composition." (PMID 39339759, 2024). "Although generally considered safe for most individuals, recommending intermittent fasting to patients with type 2 diabetes undergoing insulin or sulfonylureas therapy poses challenges due to the risk of hypoglycemia." (PMID 39229586, 2024). "The key pathomechanisms of type 2 diabetes are impaired insulin sensitivity combined with a progressive loss of pancreatic beta-cell function." (PMID 39013634, 2024). "Generally, T1D results from destruction of pancreatic β-cells, which causes defective secretion of insulin, while Type 2 diabetes arises from insulin resistance." (PMID 38166933, 2024). "Our results revealed that insulin was reduced in association with elevation of glucose levels, which proven the induction of type-2 diabetes in rats." (PMID 38528644, 2024). "Our study demonstrates that SGLT2i therapy is associated with a reduced risk of DMO in individuals with type 2 diabetes taking insulin." (PMID 38584180, 2024). "The accumulation of intrahepatic and intrapancreatic fat is one of the key mechanisms underlying pathogenesis of type 2 diabetes, which increases hepatic insulin resistance and beta-cell function, respectively." (PMID 38261560, 2024). "Conversely, both depression and schizophrenia are recognized risk factors for the onset of type 2 diabetes due to their impact on the body's resistance to insulin." (PMID 38617916, 2024). "Meanwhile, type 2 diabetes among Europeans is mainly caused by decreased insulin sensitivity, which is more closely related to obesity." (PMID 36709979, 2024). "Type 1 diabetes is mainly caused by beta cell dysfunction due to autoimmune mechanisms, whereas type 2 diabetes is caused by the heterogeneous influence of insulin resistance and beta cell dysfunction." (PMID 39168869, 2024). "Diabetes is a chronic, metabolic disease caused by elevated blood glucose levels that can be associated with an impairment of insulin production (Type 1 diabetes or T1D) or insulin resistance (Type 2 Diabetes or T2D)." (PMID 39682771, 2024). "Biphasic insulin secretion is an intrinsic characteristic of the pancreatic islet and has clinical relevance due to the loss of first-phase in patients with Type 2 diabetes." (PMID 38989001, 2024). "In chronic hyperglycemia, associated with type 2 diabetes (T2D), insufficient insulin secretion from pancreatic β-cells usually occurs." (PMID 39374805, 2024).
type 2 diabetes (continued). "So, reducing hyperinsulinemia by GLP-1 analogies will contribute to weight loss and improve insulin sensitivity, and glycemic control in type 2 diabetes." (PMID 38890501, 2024). "FGF21 can also up-regulate the secretion of adiponectin, an adipokine that plays a vital role in sensitizing the body to insulin, and hypoadiponectinemia caused by various factors can lead to obesity, type 2 diabetes, and metabolic syndrome." (PMID 38292187, 2024). "Variations or low expression of TFB1M have been associated with decreased insulin secretion in type 2 diabetes patients." (PMID 38809515, 2024). "In contrast, altered beta cell [Ca2+]i dynamics linked to defective insulin secretion and glucose tolerance have been described in animal models of type 2 diabetes and in islets from humans with type 2 diabetes." (PMID 38814444, 2024). "The recovery of normal hepatic insulin sensitivity was observed in people with type 2 diabetes after considerable weight loss and substantial reductions in intrahepatic fat deposition." (PMID 39769002, 2024). "Type 2 diabetes (T2D) is a metabolic disease characterized by chronic hyperglycemia and insulin dysregulation that significantly elevates the risk for Alzheimer’s disease (AD) by more than 60%1–3." (PMID 39713369, 2024). "Large-scale EWAS found cg02370100 to be associated with type 2 diabetes, serum triglycerides, and fasting insulin." (PMID 39695878, 2024). "KEGG pathway analysis revealed enrichment of pancreas-related functions associated with type II diabetes mellitus, insulin secretion and metabolic pathways." (PMID 38654010, 2024). "Hyperglycemia, increased insulin, and type 2 diabetes likely increase the risk of cardiovascular disease." (PMID 38459184, 2024). "Given the connection between physical activity and inflammation in the insulin-resistant group, incorporating more physical activity into the daily lives of individuals at risk of developing type 2 diabetes (DM2) holds promise as a preventive measure." (PMID 38337673, 2024). "In most studies, insulin therapy in type 2 diabetes is associated with increased fracture risk, with some studies finding the type 2 diabetes-related fracture risk only in insulin users." (PMID 38761257, 2024). "GLP-1 receptor agonists enhance insulin secretion, delay gastric emptying, and reduce appetite, aiding weight loss in obesity and improving metabolic parameters in related diseases like type 2 diabetes." (PMID 39125390, 2024). "Since obesity is a main risk factor for type 2 diabetes, hyperaldosteronism in obese patients can contribute to a change in glucose tolerance both by affecting insulin secretion and by changing insulin sensitivity." (PMID 37628857, 2023). "All genome-wide significant genetic variants were then used to separate the independent genetic effects of high childhood BMI from those of high adulthood BMI on the risk of type 2 diabetes and insulin-related phenotypes using Mendelian randomisation." (PMID 37280435, 2023). "In the same samples, INS expression was reduced and SGK1 gene induction, which has been associated with insulin release and type 2 diabetes, was inhibited." (PMID 37250333, 2023). "Type 2 diabetes mellitus (T2DM) is a metabolic disorder characterized by hyperglycemia caused by defects in insulin secretion and/or action due to a complex network of pathological conditions." (PMID 38027021, 2023). "Both findings indicate an improvement in glucose metabolism, and potentially in insulin sensitivity, which is favourable for this group of women with increased risk of type 2 diabetes." (PMID 37752466, 2023). "In type 2 diabetes, as the most common and lifestyle-dependent variant, the cellular actions of insulin including its stimulatory effect on glucose uptake is impaired, resulting in increased blood glucose levels (hyperglycemia)." (PMID 37049441, 2023).